BRCA1 (BRCA1 DNA repair associated)
Diseases named in the same sentence as BRCA1 in open-access papers (continued):
Sharing a sentence is not in itself a finding about the gene and the disease.
hereditary cancer (continued). "Loss-of-function mutation of BRCA1 in familial cancer may abolish its inhibitory role, leading to constitutive hyperactivation of the IGF1R gene, a typical hallmark of cancer cells." (PMID 28706506, 2017). "Many sporadic tumors share biological characteristics with BRCA1/2-associated hereditary cancers." (PMID 27555886, 2016). "Given the significant importance of the BRCA1 network in all proliferating cells, insights into the underlying mechanisms of BRCA1 function on chromatin might extend beyond hereditary cancers." (PMID 25426449, 2014). "While clinical trials have been conducted for the use of PARP-1 inhibitors in the treatment of cancer, the focus of PARP-1 inhibition was concentrated on its use to obtain synthetic lethality in familial cancers, such as those with a BRCA1/2 mutated phenotypes." (PMID 24202328, 2013). "In addition, the establishment of an NGS platform in Institut Pasteur de Tunis, allowed the setting up of molecular diagnosis of familial cancers, thus contributing to the better characterization and widening of the mutation spectrum of BRCA1/2 genes in the Tunisian population." (PMID 34828426, 2021). "Mutations in the BRCA1 and BRCA2 genes significantly increase the risk of hereditary cancers, mainly of the breast and ovary, but also of other cancers such as those of the pancreas, prostate and cervix." (PMID 40949480, 2025). "This study finds that NGS testing of normal tissue using a 37-gene hereditary cancer panel, including BRCA1/2, shows 100% concordance with known germline findings in cases of HGSOC." (PMID 41300712, 2025). "Machine learning-based pathogenicity prediction helps interpret rare missense variants of BRCA1 and BRCA2, which are associated with hereditary cancers." (PMID 37380723, 2023). "Second, the study did not have access to personal history, family history, and status of genetic mutations, such as those in BRCA1/BRCA2, which influence hereditary cancer." (PMID 37781206, 2023). "The finding of low BRCAness measured by HRDetect among non-BRCA1/BRCA2 familial cancer indicates a low false positive rate for the classification of VUS in this clinically relevant patient group." (PMID 37316882, 2023). "We compared our results with the BRCA1 and BRCA2 mutational spectrum reported by the Brazilian Consortium of Hereditary Cancer, as well as other studies." (PMID 35353237, 2022). "Although the BRCA1 (NM_007294.3) and BRCA2 (NM_000059.3) gene variants were the primary focus of such studies in the past, hereditary cancer panel testing has recently replaced the approach involving only the BRCA1 and BRCA2 genes." (PMID 33558524, 2021). "For a common disease like cystic fibrosis, the estimated clinical sensitivity was 99.90%, with PPV, specificity, and NPV all >99.9%, comparable to levels of clinical validity reported for hereditary cancer screening of BRCA1/2." (PMID 31170325, 2019). "Conventional methods used to identify BRCA1 and BRCA2 germline mutations in hereditary cancers, such as Sanger sequencing/multiplex ligation-dependent probe amplification (MLPA), are time-consuming and expensive, due to the large size of the genes." (PMID 31065452, 2019). "The mutation spectrum of BRCA1 and BRCA2 mutations in the largest hereditary cancer clinic in Norway is diverse." (PMID 29339979, 2018). "The field of hereditary cancer has changed significantly since the discovery of the BRCA1 and BRCA2 genes in the mid-1990s, and it is important that models of genetic service delivery evolve as well." (PMID 30428547, 2018). "Because of the potential to miss such mutations, re-testing of individuals who previously had limited BRCA1 and BRCA2 testing should be considered, particularly in ethnicities with elevated risk or if a strong suspicion for hereditary cancer otherwise remains." (PMID 28281021, 2017).
hereditary cancer (continued). "The discovery of BRCA-ness (HR-ness) in a subset of sporadic tumors significantly extends potential indications for the drugs, which were initially considered to be active only in BRCA1/2-related hereditary cancers." (PMID 27555886, 2016). "Breast-ovarian hereditary cancer syndrome is by far more common than other categories of familial cancers, with BRCA1 and BRCA2 being among the most studied genes." (PMID 27555886, 2016). "This association confirmed the predominant involvement of HIF-1α in the development of angiogenesis in familial cancers and specifically in BRCA1-2 carrier cancers." (PMID 23326384, 2013). "Mutations of the BRCA1 and BRCA2 genes, encoding two proteins involved in DNA repair, underlie most cases of such hereditary cancers." (PMID 23354980, 2013). "When we considered all familial cancers (BRCA1-2 and BRCAX), the cytoplasmic VEGF expression was positive in 79% (66/83) of cases." (PMID 23326384, 2013). "VEGF immunoreactivity was correlated with poor tumor grade (p = 0.0074), hormone receptors negativity (p = 0.0206, p = 0.0002 respectively), and MIB-1-labeling index (p = 0.0044) in familial cancers (BRCA1-2 and BRCAX)." (PMID 23326384, 2013). "Epimutation of DNA mismatch repair (MMR) genes (BRCA1, hMLH1 and hMSH2) involved in development familial cancers has also been found." (PMID 22735547, 2012). "Levels of cancer-specific worry are lower in this cohort than those previously reported in other familial cancer studies: median=8 compared to scores for a cohort offered BRCA1/2 predictive genetic testing, median=11." (PMID 16434991, 2006). "This applies to familial cancers, i.e., BRCA1-2 gene carriers." (PMID 40429943, 2025). "Analysis of hereditary cancer cases (732 BC patients, 189 CRC patients, and 490 cancer-free elderly controls) revealed that 1% presented concurrent germline pathogenic variants in BRCA1, BRCA2, MUTYH, ATM, CHECK2, NBN, and RAD50." (PMID 37628631, 2023). "Large studies into non-BRCA1/2 familial cancers are also needed." (PMID 36831687, 2023). "For example, Brca1 and Brca2 are tolerant of variation, ranking among the 9% ad 8% least constrained mouse genes; however, their human orthologues BRCA1 and BRCA2 contain high numbers of pathogenic variants that are causally linked to adult-onset hereditary cancer." (PMID 37736706, 2023). "Notably, epigenetic inactivation of the WRN gene was introduced as a common event in sporadic colorectal tumorigenesis as described for other DNA repair tumor suppressor genes, hMLH1 and BRCA1, involved in hereditary cancers." (PMID 34164337, 2021). "The percentage of BRCA1 mutations in women diagnosed with triple negative breast tumors, without any selection for familial cancer, increases up to 28%." (PMID 30630528, 2019). "In patients with ovarian cancer, without any selection for familial cancer, the BRCA1 ex9-12del mutation was detected in 33% of the cases, supporting the notion that this is a founder mutation in Mexico." (PMID 30630528, 2019). "A Delphi survey of 16 expert genetics and cancer health professionals and 16 service users with cancer and a BRCA1/BRCA2 pathogenic variant agreed that information about inheritance, genetic testing, cancer risks and the management of hereditary cancer were key messages for cancer patients." (PMID 30573802, 2019).
hereditary cancer (continued). "In addition, we found a positive correlation between MVD and HIF-1α in BRCA1-2 carrier and in all familial cancers, confirming a major aggressiveness of these tumor phenotypes." (PMID 23326384, 2013). "Therefore, in all familial cancers (BRCA1-2 and BRCAX) the VEGF expression was more intensive (HIS score 5) than in sporadic cancers (HIS score 2) (p<0.0001)." (PMID 23326384, 2013). "Unfortunately, most studies comparing sporadic to hereditary cancers failed to stratify results by histological type, making it difficult to compare serous cases in BRCA1 mutation carriers to their sporadic counterparts." (PMID 19636370, 2009). "Screening for the mutations carried out in several groups suggested significant variation of the relative contribution of BRCA1 and BRCA2 genes to hereditary cancer among the populations." (PMID 24711893, 2014). "The possible involvement of genes like BRCA1, BRCA2, CHEK2, and POT1, which are known to play a role in other hereditary cancers, could lead to new knowledge of UM, especially in family cases." (PMID 39926282, 2025). "This heterogeneity is currently not considered in daily clinical practice, e.g., BRCA1/2 LOH or HRD testing is not incorporated in the decision-making process for patients with hereditary cancers." (PMID 34454564, 2021). "In our analysis one of the BRCA1, BRCA2, RAD51C, and PALB2 mutations was found in 25.8% of familial cancer cases and in 9.9% of non-familial cases, similar to what has been reported previously." (PMID 33670479, 2021). "We selected 25 hereditary cancer-related genes not including BRCA1/2 and designed a customized gene panel, which covered 97.6% of target regions in these genes." (PMID 26436112, 2015). "BRCA1 c.5407-25T>A had initially been classified as a VUS in ClinVar based on two submissions of its identification in the context of HBC or HBOC and five independent studies published prior to 2020 that also described its identification in this hereditary cancer context." (PMID 35456503, 2022). "Notably, 19% of BRCA1 or BRCA2 mutation carriers identified did not have a family history suggestive of hereditary breast and ovarian cancer syndrome and thus would not have been referred for, nor qualified for hereditary cancer testing." (PMID 29506471, 2018).
lung carcinoma (138 papers, 2005 to 2025). "We observed that geldanamycin partially induced synthetic lethality with FHIT loss in lung cancer cells, accompanied by the downregulation of BRCA1 and RAD51 levels." (PMID 39762409, 2025). "All FHIT-deficient lung cancer cells presented increased expression levels of BRCA1 and RAD51 and increased levels of phosphorylated DNA-PKcs." (PMID 39762409, 2025). "One study reported that the polymorphisms of BRCA1 rs799917 were associated with the response to chemotherapy and the overall survival of Korean lung cancer patients." (PMID 40361383, 2025). "Homologous repair genes have been implicated in the survival of lung cancer patients post-treatment, with mixed clinical outcomes in cases involving BRCA1 mutations." (PMID 38989152, 2024). "We found that 1.17% of 1117 unselected Chinese lung cancer patients carried BRCA1 (0.54%) and BRCA2 (0.63%) P/LP variants." (PMID 37930190, 2023). "Gene-based burden test showed that 9.52% and 6.78% of individuals with breast and lung cancer had predicted loss of function variants in BRCA1 and BRCA2, respectively." (PMID 37461096, 2023). "Compared to the controls, enrichment of BRCA1 variants in lung cancer patients was statistically significant, with an OR of 4.193 (95% CI 1.382–10.768, p = 0.006), but it was not significant for BRCA2." (PMID 37930190, 2023). "We observed that lung cancer was more common in families of BRCA2 c.9976A>T carrier probands (0.22) when compared to BRCA1/2 wild type (0.13) or pathogenic BRCA1 (0.09) or BRCA2 (0.09) variant carrier families." (PMID 33672545, 2021). "Lung cancer was more prevalent in families carrying the c.9976A>T variant compared to pathogenic BRCA1 or BRCA2 carrier families." (PMID 33672545, 2021). "In order to develop such a diagnostic method, we first analyzed the BRCA1/2 mutant lung cancer cases." (PMID 34145376, 2021). "Whole exome sequencing of the lung cancer has revealed a germline BRCA1 deficiency mutational signature." (PMID 33880365, 2021). "Materials and Methods: Observation studies were systematically reviewed to explore the association of BRCA1 or BRCA2 with lung cancer." (PMID 32349445, 2020). "Although PARP inhibitor treatment in patients with a range of tumor types with germline BRCA1/2 mutations have shown to be effective, such mutations are only found in ~5% of patients with lung cancer." (PMID 32850380, 2020). "Some small subsets investigated the association between germline BRCA1/2 mutation and EGFR-mutant lung cancer, but didn’t have positive findings due to the rare frequency of the BRCA1/2 germline mutations." (PMID 31703574, 2019). "In the lung cancer cell lines, a similar correlation was found, including a strong association between BRCA1 and AEG-1 expression." (PMID 21951562, 2011). "Recently studies have shown a possible association between lung cancer and BRCA1 and BRCA2 mutation." (PMID 16721370, 2006). "The association of RUNX2 and BRCA1 with the osteoblastic lineage may suggest that its dysregulation in lung cancer may occur in the formation of coregulatory complexes, thereby affecting the function of multiple essential genes in lung pathologies." (PMID 36551878, 2022). "However, lung cancer was more prevalent in families carrying c.9976A>T compared to pathogenic BRCA1/BRCA2 carrier families." (PMID 33672545, 2021).
lung carcinoma (continued). "Due to having high TMB, BRCA1/2 germline mutation related tumors are considered to be candidates for immune checkpoint inhibition strategies, which were successful in highly mutated melanoma and lung cancers." (PMID 32164626, 2020). "Furthermore, one carrier who developed lung cancer was a homozygote and, since this is the second time homozygosity of this variant in an adult is reported, BRCA1 c.4096+3A>G must be highly unusual compared to previously analyzed BRCA1-mutations." (PMID 31683985, 2019). "Heterozygous NBS1 splicing mutation (IVS11+2insT) detected in sporadic gastric, colorectal and lung cancers led to defects in crucial binding to Mre11, Mdc1 and BRCA1, and caused impaired ATM phosphorylation in response to low-dose irradiation in the heterozygous state." (PMID 24349281, 2013). "Genes whose expression showed a positive correlation with NFY expression and mevalonate pathway genes were found to exhibit protein-protein interactions with several ‘hub’ genes, including BRCA1, that have been associated with both lung cancer and cell division." (PMID 22211244, 2012). "The TC/CC genotypes of BRCA1 rs1799966 were associated with a lower risk of death (hazard ratio = 0.617, p = 0.028), and the C allele (TC + CC vs. TT) of rs1799966 was associated with a good response to chemotherapy (OR = 0.402, p = 0.008) in patients with lung cancer in the Chinese population." (PMID 40361383, 2025). "Notably, the pretreatment primary tumor biopsy of our patient with lung cancer had an HRD-sum score of 25 that is higher than the median of 14 for BRCA1/2 mutated tumors at similar purity levels, further affirming the HRD phenotype of the pre-treatment lung tumor." (PMID 36418296, 2022). "We showed that a GSK3β inhibitor selectively inhibited FHIT-deficient lung cancer by inhibiting the ATR/BRCA1/RAD51 signaling axis and BRCA1/RAD51 transcription, leading to the inhibition of HRR and genotoxic cell death." (PMID 39762409, 2025). "Analysis of tumor samples revealed that BRCA1 and RAD51 levels were elevated in FHIT-deficient lung cancer, and CHIR99021 treatment reduced their protein levels." (PMID 39762409, 2025). "Research by Margeli, Taron, and their colleagues has demonstrated that lower BRCA1 expression predicts improved outcomes in lung cancer patients." (PMID 38989152, 2024). "In this study, the clinicopathological, survival, immune infiltration, and BRCA1 expression data of lung cancer patients retrieved from public databases and relevant articles were analyzed." (PMID 38090061, 2023). "Carriers of BRCA1 and BRCA2 P/LP variants accounted for 0.79% and 0.60% of 1017 lung cancer patients with adenocarcinoma or squamous cell carcinoma, respectively, in the TCGA cohort." (PMID 37930190, 2023).